TBK1 (TANK binding kinase 1)
Diseases named in the same sentence as TBK1 in open-access papers (continued):
Sharing a sentence is not in itself a finding about the gene and the disease.
viral infection (continued). "Given that PTK2B and TBK1 could co-localize together and form cellular granules upon HSV-1 infection, we reasoned that PTK2B could potentially undergo oligomerization, in response to virus infection." (PMID 37989995, 2023). "However, our results show that viral infection or genetic knockout of lincRNA‐EPS facilitates PKR‐STAT1 signaling axis induced antiviral genes such as Mx1, Oas2, Ifit2, and Irf7, while inhibits phosphorylation of TBK1 and IRF3, as well as the IFN‐β induction." (PMID 35312140, 2022). "Mechanistically, we demonstrated that TRIM18 recruited the protein phosphatase PPM1A to dephosphorylate TBK1, which inactivated TBK1 and blocked interactions of TBK1 with its upstream adaptors MAVS and STING, dampening type I IFN mediated antiviral signaling during virus infection." (PMID 35909127, 2022). "Decreased phosphorylation of IRF7 and TBK-1 in CD14dimCD16+ monocytes, cDC1, and cDC2 from older donors impairs the production of IFN downstream of TLR7/8 and RIG-I pathways in primary antiviral responses and the ability of these cells to respond quickly to viral infection." (PMID 35849213, 2022). "The multi-faceted antiviral nature of TBK1 make it a very promising therapeutic target to limit viral replication and spread; thus, additional studies must be done to further characterize in vivo use of TBK1-activating agents to limit CVB infection and subsequent viral disease." (PMID 36044516, 2022). "Upon viral infection, these PRRs recruit different key adaptor protein, such as TIR domain-containing adapter-inducing interferon-β (TRIF), mitochondria antiviral-signaling protein (MAVS), or stimulator of interferon genes (STING), which then triggers the activation of TANK-binding kinase 1 (TBK1)." (PMID 33584728, 2020). "However, follow-up studies demonstrated that IKKε is also critically involved in IFN-β induction, and both IKKε and TBK1 are required for optimal IFN induction upon virus infection, suggesting important non-redundant roles for IKKε, and TBK1." (PMID 32656094, 2020). "After viral infection, pattern recognition receptors detect viral molecular features and activate the essential transcriptional regulator IRF3 via phosphorylation of its C-terminal trans-activation domain by TBK1/IKKε, and trigger the production of type I IFNs." (PMID 31618847, 2019). "Importantly, a minimal amount of IFNs was produced independent of NF-κB activation during virus infection and that individual TRAFs differently mediated TBK1/IKKε activation, thus fine-tuned antiviral immunity under physiological conditions." (PMID 29125880, 2017). "However, viral infection or cIAP1/2 overexpression did not cause noticeable degradation of TRAF3/6, and activation of downstream kinases such as TBK1 and TAK1 were proposed." (PMID 27716849, 2016). "Following virus infection, activation of the RIG/MAVS pathway leads to TBK1 activation (presumably through phosphorylation by an upstream unknown kinase and ubiquitination by the E3 ligases MIB1/2 or Ndrp1) and to the disruption of its interaction with Optn and CYLD." (PMID 25923723, 2015). "TBK1 and IKKε were spatially separated from VP35 upon infection by EBOV trVLPs, and IRF3 itself was demonstrated not to interact with VP35 and NP, implying that other IRF3-interacting proteins might be involved in IRF3 sequestration in IBs upon viral infection." (PMID 38285487, 2024). "The upstream kinase activating TBK1 in response to viral infection is not yet known, although genetic and pharmacological studies suggested that TBK1 could be activated by IKKβ, as well as by autophosphorylation that can be facilitated by Glycogen Synthase Kinase (GSK)-3β interaction." (PMID 25923723, 2015). "Additionally, upon viral infection, vimentin expression is increased, which may be influenced by IFN receptor 1 (IFNAR1), a nonspecific factor triggered by almost all viral infections, can inhibit TBK1 and IKKε during the process of enhanced vimentin expression." (PMID 37376653, 2023).
viral infection (continued). "Initial evidence indicated a more important role for TBK1, rather than IKKε, in the induction of type I IFN in response to dsRNA and virus infection." (PMID 32656094, 2020). "The second model suggests that MAVS recruits TBK1 through TBK1 binding proteins NAP1 or SINTBAD, however knock-down of these two proteins did not impair type I-IFN production after viral infection." (PMID 29125880, 2017). "Our studies indicate that viral infection with Newcastle Disease Virus (NDV) does not activate IRF5, although expression of kinases that function during viral infection, TBK-1 or NF-κB kinase-ε (IKKε), can phosphorylate IRF5." (PMID 22412986, 2012). "Furthermore, under the following conditions: without viral infection, during VSV infection, and during NDV infection, overexpression of bat TBK1 all enhanced IRF3-mediated upregulation of IFNβ expression." (PMID 40791583, 2025). "It has been observed that IKKε and TBK1 share a similar substrate phosphorylation motif in vitro; however, genetic knockout studies have shown that TBK1, not IKKε, is crucial for IFN induction in response to viral infections." (PMID 39823515, 2025). "Since TBK1 is activated by RLR signaling during RNA virus infection, we hypothesized that TBK1 phosphorylates AIP during virus infection as part of a negative feedback mechanism." (PMID 38043800, 2023). "By incubating Calu-1 cells with IMD-0354 (without subsequent viral infection), we also observed increased expression of IFN-β, CXCL10, and IL-6 with 15, 9, and 36-folds, respectively; and the activation of these genes was counteracted by BX795, a TBK1/IKKε inhibitor that blocks IFN-β production." (PMID 36093376, 2022).
frontotemporal dementia (64 papers, 2015 to 2026). Frontotemporal dementia (FTD) comprises a group of neurodegenerative disorders, characterized by progressive changes in behavior, executive dysfunction and language impairment, as a result of degeneration of the medial prefrontal and frontoinsular cortices. "TBK1 functions in innate immunity, and mutations in TBK1 have been linked to both amyotrophic lateral sclerosis and frontotemporal dementia." (PMID 40905990, 2025). "The variants classified as pathogenic by MoVUS in TBK1 were present in two patients at the UCSF MAC with confirmed clinical diagnoses of frontotemporal dementia." (PMID 41256702, 2025). "We also identified TBK1, a kinase that when disrupted causes frontotemporal dementia/ALS and induces dendritic spine loss in animal models." (PMID 37268664, 2023). "TBK1 is a serine-threonine protein kinase that has been linked to a number of diseases including amyotrophic lateral sclerosis and frontotemporal dementia." (PMID 36415206, 2022). "Protein aggregation of TARDBP/TDP-43 is a hallmark of amyotrophic lateral sclerosis (ALS) and frontotemporal dementia (FTD) pathology which has specifically been described in motor neurons harboring TBK1 mutations." (PMID 40396014, 2022). "TANK-binding kinase 1 (TBK1) mutations are a recently discovered cause of disorders in the frontotemporal dementia (FTD)–amyotrophic lateral sclerosis (ALS) spectrum." (PMID 32980182, 2021). "The mutation of TANK‐binding kinase 1 (TBK1) gene has been regarded as a causative gene of frontotemporal dementia (FTD)‐amyotrophic lateral sclerosis (ALS) spectrum disease in recent years." (PMID 30672142, 2019). "Mutations in the TANK-binding kinase 1 (TBK1) gene have recently been shown to cause frontotemporal dementia (FTD) and amyotrophic lateral sclerosis (ALS)." (PMID 31160356, 2019). "Mutations in the TANK-binding kinase 1 (TBK1) gene have recently been shown to cause frontotemporal dementia (FTD)." (PMID 28229125, 2017). "Furthermore, a TBK1 mutant (E696K) associated with amyotrophic lateral sclerosis and frontotemporal dementia constitutively accumulates at lysosomes, resulting in elevated Rab7 phosphorylation and increased mTORC1 activation." (PMID 38168426, 2023). "We report a 74-year-old female with frontotemporal dementia (FTD) linked to a pathogenic TANK-binding kinase 1 (TBK1) mutation (c.1349_1352del (p.Ile450Lysfs*15))." (PMID 40713844, 2025). "Several variants of the TANK-Binding Kinase 1 (TBK1) gene have been associated with frontotemporal dementia - amyotrophic lateral sclerosis (FTD-ALS) spectrum diseases." (PMID 35309588, 2022). "The TANK-Binding Kinase 1 (TBK1) gene has recently been identified as the third or fourth most frequent cause of frontotemporal dementia (FTD) and amyotrophic lateral sclerosis (ALS)." (PMID 30534373, 2018). "Mutations in the TANK-binding kinase 1 (TBK1) gene represent a significant genetic link across the Amyotrophic Lateral Sclerosis (ALS) and Frontotemporal Dementia (FTD) spectrum." (PMID 41827910, 2026). "There exists a genetic, clinical, and pathological overlap between ALS and frontotemporal dementia (FTD), whereby several genes (e.g., C9orf72, TARDBP, TBK1) have been associated with both conditions." (PMID 38986433, 2025). "Two patients were classified as TAR DNA-binding protein 43 (TDP-43)-positive frontotemporal lobar degeneration FTLD-TDP: one FTLD/MND-TDP; one FTLD-TDP related to a TANK-binding kinase 1 (TBK1) mutation." (PMID 40100387, 2025). "Heterozygous mutations in the TBK1 gene can cause amyotrophic lateral sclerosis (ALS) and frontotemporal dementia (FTD)." (PMID 38517332, 2024). "TBK1-related diseases include cancer therapy, inflammation, autophagy, acute infectious diseases, and frontotemporal dementia." (PMID 38962149, 2024).
frontotemporal dementia (continued). "Our study aims to evaluate the genetic and phenotypic spectrum of Frontotemporal dementia (FTD) gene variant carriers in Chinese populations, investigate mutation frequencies, and assess the functional properties of TBK1 and OPTN variants." (PMID 38872230, 2024). "Gene mutations in both OPTN and TBK1 have been found in patients suffering from amyotrophic lateral sclerosis (ALS) and frontotemporal dementia (FTD), suggesting physiological and molecular links between OPTN and TBK1." (PMID 38287189, 2024). "TBK1, which encodes TANK-binding kinase 1 (TBK1), has been identified as a causative gene in ALS with frontotemporal lobar degeneration (FTLD-ALS4)." (PMID 37967220, 2023). "In support of a critical role for autophagy in ALS pathogenesis is the discovery of mutations in the autophagic kinase TBK1 as a cause of inherited ALS and frontotemporal dementia." (PMID 36226074, 2022). "For example, hyperactivation of RIPK1 in Tbk1/Tak1 double heterozygous mice leads to comorbidity of amyotrophic lateral sclerosis (ALS) and frontotemporal dementia (FTD), which is attenuated by one allele of kinase-dead RIPK140." (PMID 34862394, 2021). "Exome sequencing has identified TBK1 as a risk factor in ALS and fronto-temporal dementia with mutations in the human TBK1 gene implicated in neuroinflammatory disorders." (PMID 33633536, 2021). "Haploinsufficiency of the protein kinase Tbk1 has shown to cause both amyotrophic lateral sclerosis (ALS) and frontotemporal dementia (FTD); however, the pathogenic mechanisms are unclear." (PMID 31039129, 2019). "Mutations in the tumor necrosis factor receptor-associated factor NF-κB activator (TANK)-binding kinase 1 (TBK1) gene, located on Chromosome 12, have recently been described as a cause of familial frontotemporal dementia (FTD) and amyotrophic lateral sclerosis (ALS)." (PMID 31160356, 2019). "It has been discovered that mutations in TBK1 are associated with several central nervous system (CNS) diseases: amyotrophic lateral sclerosis (ALS), frontotemporal dementia (FTD), normal tension glaucoma (NTG), and childhood herpes simplex encephalitis (HSE)." (PMID 30223576, 2018). "Mechanistically, TBK1 inactivates RIPK1 by phosphorylating RIPK1 at Thr189, and loss of TBK1 boosts RIPK1 activation and aggravates late-onset ALS/frontotemporal dementia-like pathology, providing insights on intermolecular regulation between TBK1 and RIPK1 in ALS." (PMID 40328798, 2025). "Mutations in TBK1 cause amyotrophic lateral sclerosis (ALS) and frontotemporal dementia (FTD)." (PMID 38517332, 2024). "Seven patients were classified as having definite PSP, and two patients were classified as having TAR DNA-binding protein 43 (TDP-43)-positive frontotemporal lobar degeneration (FTLD-TDP): one with FTLD/MND-TDP and one with FTLD-TDP related to a TANK-binding kinase 1 (TBK1) mutation." (PMID 39580770, 2024). "Missense mutations in TANK-binding kinase 1 (TBK1) have diverse biophysical and biochemical effects on the molecule and are associated with the neurodegenerative diseases amyotrophic lateral sclerosis (ALS) and fronto-temporal dementia." (PMID 34099552, 2021). "More than 90 distinct mutations in TBK1 are linked to amyotrophic lateral sclerosis (ALS) and fronto-temporal dementia, including missense mutations that disrupt the abilities of TBK1 to dimerize, associate with the mitophagy receptor optineurin (OPTN), autoactivate, or catalyze phosphorylation." (PMID 34099552, 2021). "An overview of recently proposed ALS genes that were identified based on rare genetic variants (TBK1, CHCHD10, TUBA4A, CCNF, MATR3, NEK1, C21orf2, ANXA11, TIA1) and their potential relevance to the genetic etiology of frontotemporal dementia have also been described." (PMID 33805659, 2021).
frontotemporal dementia (continued). "Also, recent advances of TBK1 biology in neuronal function have proposed its association to amyotrophic lateral sclerosis (ALS) and fronto-temporal dementia in humans by impaired autophagy/mitophagy, leading to retinal cell death in ALS." (PMID 30866491, 2019). "This hypothesis have been very recently underscored by two studies identifying TBK1 as an ALS gene and showing that haploinsufficiency of TBK1 such as observed in the case of Optn-interaction mutant of TBK1, causes ALS and fronto-temporal dementia." (PMID 25923723, 2015). "Dysfunction of TBK1 is linked to a number of human diseases, most prominently (ALS) and ALS/frontotemporal dementia (ALS/FTD), but also herpes simplex encephalitis (HSE), diabetes, obesity, cancer, and normal tension glaucoma (NTG)." (PMID 41191168, 2025). "Repeat expansions in C9orf72 and mutations in TBK1 have established associations with both ALS and frontotemporal dementia (FTD)." (PMID 40202986, 2025). "Heterozygosity for predictedLOF (pLOF) mutations of TBK1 was subsequently shown to be linked to neurodegenerative diseases, such as amyotrophic lateral sclerosis (ALS) and frontotemporal dementia (FTD) in particular." (PMID 41608123, 2025). "Heterozygous loss-of-function mutations in the TBK1 gene cause amyotrophic lateral sclerosis (ALS) and frontotemporal dementia (FTD)." (PMID 39103493, 2024). "TANK-binding kinase 1 (TBK1) phosphorylates SQSTM1 and OPTN, and haploinsufficiency of TBK1 is associated with both ALS and frontotemporal dementia (FTD)." (PMID 37307819, 2024). "Multiple loss-of-function mutations on TBK1 gene have been identified across sporadic and familial instances of ALS, as well as in cases of ALS/frontotemporal dementia (ALS-FTD/FTD)." (PMID 38443977, 2024). "Heterozygousity in TBK1 has been linked with the onset of familial amyotrophic lateral sclerosis (ALS) and frontotemporal dementia (FTD) in aging." (PMID 36969188, 2023). "Mutations in FUS and TBK1 often cause aggressive early-onset amyotrophic lateral sclerosis (ALS) or a late-onset ALS and/or frontotemporal dementia (FTD) phenotype, respectively." (PMID 34518945, 2022). "More than 90 mutations in TBK1, such as non-sense mutations, frameshift, out-frame, and splice-site, have been reported to result in loss of function (LoF) of the TBK1 and lead to ALS or frontotemporal dementia (FTD)." (PMID 35283724, 2022). "Similar to OPTN, TBK1 has been linked to familial forms of normal tension glaucoma, and ALS combined with frontotemporal dementia (FTD)." (PMID 34201955, 2021). "Furthermore, an aging-induced reduction in TAK1 expression combined with TBK1 mutations promotes the onset of neurodegenerative diseases, including ALS and frontotemporal dementia (FTD)." (PMID 39062098, 2024). "Furthermore, human TBK1 mutations that cause elevated RIPK1 activity and neuroinflammation in the central nerve system result in ALS/frontotemporal dementia (FTD) comorbidity." (PMID 34862394, 2021). "Mutations of the TBK1 gene are connected to several diseases, including childhood herpes simplex encephalitis (HSE), amyotrophic lateral sclerosis (ALS), frontotemporal dementia (FTD), and normal-tension glaucoma (NTG) (reviewed in30)." (PMID 34226595, 2021). "Haploinsufficiency of Tbk1, resulting from heterozygous loss-of-function mutations causing ~50% reduction in Tbk1 levels, has been recently identified as a cause for ALS and frontotemporal dementia (FTD)." (PMID 31039129, 2019). "As a result, research has been focused on understanding contributions of TBK1 to various human diseases, such as amyotrophic lateral sclerosis (ALS), frontotemporal dementia (FTD), NTG, childhood herpes encephalitis (HSE), autoimmune diseases, cancer, and viral infections." (PMID 41567509, 2025).
frontotemporal dementia (continued). "TANK-binding kinase 1 (TBK1) has emerged as one of the most compelling genetic contributors to amyotrophic lateral sclerosis (ALS), with heterozygous loss-of-function and pathogenic missense variants identified in patients across the ALS–frontotemporal dementia (FTD) spectrum." (PMID 41302089, 2025). "A better understanding of TARDBP and TBK1 could also lead to a better understanding of how they may be responsible for two pathologies, ALS and fronto-temporal dementia (FTD)." (PMID 39201350, 2024). "Interestingly, numerous human TBK1 mutations have been identified in patients with neurodegenerative diseases such as amyotrophic lateral sclerosis (ALS), as well as frontotemporal dementia (FTD), highlighting a role for TBK1 in the CNS." (PMID 30794036, 2019). "Up to 15% of ALS patients also develop signs of frontotemporal dementia (FTD) and several genes, including C9ORF72, TDP-43, VCP, SQSTM1, OPTN, UBQLN2 and TBK1, contribute to the etiology of both ALS and FTD." (PMID 37220877, 2023). "Given the patient’s family history of frontotemporal dementia (FTD) in a maternal uncle, the genetic analysis was extended to include the most common genes associated with FTD (TARDBP, GRN, TBK1, CHMP2B, SQSTM1, UBQLN2, VCP and MAPT) but no additional variants of clinical significance were detected." (PMID 40659544, 2025).